ADCY3 (adenylate cyclase 3)
Diseases named in the same sentence as ADCY3 in open-access papers (continued):
Sharing a sentence is not in itself a finding about the gene and the disease.
depression (13 papers, 2012 to 2025). "A dmCpG from Analysis 4 was located within ADCY3, a gene that has previously been linked to major depressive disorder." (PMID 34696705, 2022). "The forebrain-specific pyramidal neuron conditional Adcy3 KO mice recapitulates many aspects of the major depressive disorder- and autism spectrum disorder-associated symptoms, but intriguingly display normal social interaction." (PMID 36188604, 2022). "GWAS studies demonstrated that ADCY3 polymorphism was associated with obesity, depression, and inflammatory bowel disease." (PMID 35307032, 2022). "ADCY3 is involved in olfactory-dependent learning and associated with major depressive disorder in humans." (PMID 35307032, 2022). "Intriguingly, the region-specific knock-down of Adcy3 in the main olfactory epithelium not only leads to anosmia but also causes depression-like behavior and cognitive defects." (PMID 36188604, 2022). "The functional relevance of Adcy3 mutations to major depressive disorder and autism spectrum disorder has been examined with the KO and knock-in mice." (PMID 36188604, 2022). "Although there are debates on the significance of genetic risk factors in human major depressive disorder, a GWAS study with 2,431 major depressive disorder and 3,673 control samples revealed a suggestive association of Adcy3 polymorphism with depression." (PMID 36188604, 2022). "Genome-wide association studies in humans have associated ADCY3 with major depressive disorder and autistic spectrum disorder, both of which exhibit sexual dimorphism." (PMID 30814930, 2019). "The results suggest a role of olfactory cAMP signaling in the association of olfaction deficiency and depression; further understanding of how ADCY3 mediates the functional cross-talk among brain circuitry networks of olfaction, emotion and cognition is critical." (PMID 36188604, 2022). "These genes include CHD7, ADCY3, ANK3, NWD1, CNTNAP2 and TSNAX-DISC1, each of which has been carefully considered and contrasted as no previous link between neural disorders or psychiatric conditions, including depression, has been made for risk preference." (PMID 34696705, 2022). "Consistently, Adcy3 mRNA level is reduced in the blood samples of major depressive disorder." (PMID 36188604, 2022). "Interestingly, variation in ADCY3 has been nominated in a number of GWAS including for alcohol dependence and major depression." (PMID 22433082, 2012). "Adenylate cyclase 3 plays an integral role in the signal transduction downstream of prostaglandin receptors, further providing evidence of a role for COX-2 inhibition in depression." (PMID 35977923, 2022). "Notably, lower PKA expression and ADCY activity in platelets, which express only Adcy3 but not other Adcy isoforms, are detected in major depressive disorder subjects and attenuated by the use of various drugs including antidepressants, analgesics, and addictive drugs." (PMID 36188604, 2022).
Insulin resistance (13 papers, 2016 to 2025). Increased resistance towards insulin, that is, diminished effectiveness of insulin in reducing blood glucose levels. "We identified a heterozygous missense variant in ADCY3 (c.3328G>C, p.G1110R) in Patient 4; a 16-year-old female with a BMI Z-score of +4.8, insulin resistance, asthma and depression." (PMID 32153512, 2020). "This insulin resistance observed in Adcy3+/− mice appears to be associated with decreased AMPK activity." (PMID 27678003, 2016). "On the other hand, hepatic ADCY3 upregulation by liraglutide was also shown to reduce body weight and improve insulin resistance in a mouse model." (PMID 32847122, 2020). "Despite the possible involvement of the GNDPA2, TMEM18, and ADCY3 loci in insulin resistance, insulin/glucagon regulation, and insulin secretion, respectively, we chose to retain them in the IV analysis." (PMID 28763444, 2017). "Insulin resistance, a core feature of MetS, is linked to genes such as CDKAL1, ADCY3, and ADRA2A." (PMID 39858569, 2024). "Interestingly, reduced expression of hepatic Adcy3 results in increased vulnerability to diet-induced hepatic insulin resistance in mice." (PMID 34069853, 2021). "The present study was aimed at determining whether Adcy3 functions in peripheral tissues related to metabolic disorders by regulating the development of adiposity and insulin resistance in mice." (PMID 27678003, 2016). "Likewise, it has been proposed that ADCY3 dysfunction in peripheral tissues could be related to metabolic disorders by inducing adipocyte dysfunction and insulin resistance in mice." (PMID 31527397, 2019). "Therefore, the increased plasma levels of proinflammatory cytokines could also be a contributing factor for the aggravated insulin resistance in Adcy3+/− mice." (PMID 27678003, 2016).
Anosmia (7 papers, 2013 to 2025). An inability to perceive odors. "Biallelic, loss-of-function mutations in ADCY3 were found to cause severe, early-onset obesity associated with anosmia, cognitive impairment, developmental delay, seizures and severe pneumonia." (PMID 39237720, 2025). "ADCY3 deficiency is involved in diverse physiological processes and health problems - from anosmia and respiratory problems to learning impairment and metabolic disorders." (PMID 39237720, 2025). "Deficiency of ADCY3, which is the only ADCY in olfactory cilia, causes anosmia (i.e., loss of smell)." (PMID 36188604, 2022).
gastric cancer (7 papers, 2013 to 2025). A primary or metastatic malignant neoplasm involving the stomach. "ADCY3 has been reported to promote gastric cancer tumorigenesis and is also associated with ovarian development and disease 33-35." (PMID 40860157, 2025). "The cAMP pathway was already found to be associated with cancer, with the overexpression of ADCY3 increasing oncogenic potential in gastric cancer cells and ADCY8 acting itself as a risk modifier in glioma." (PMID 30871259, 2019). "Our study is the first to report an association of ADCY3 with gastric cancer as well as its tumorigenic potentials." (PMID 24113161, 2013). "We also found evidence for a functional association between ADCY3 and gastric cancer, through CREB pathway-dependent effects on cell migration, invasiveness, proliferation, and clonogenicity." (PMID 24113161, 2013). "In this study, we provide the first evidence that upregulation of ADCY3 in gastric cancer cells and tissues is associated with increased tumorigenic potential." (PMID 24113161, 2013). "ADCY3 serves as an oncogene in gastric cancer formation, as an oncogene, with high ADCY3 expression regulated by DNA methylation accompanied by low survival." (PMID 35832555, 2022). "In summary, our results indicate that elevated ADCY3 expression contributes to gastric cancer progression through the cAMP/PKA/CREB pathway, by increasing both mRNA expression and MMP2 and MMP9 activity." (PMID 24113161, 2013). "To investigate the molecular pathway of ADCY3 in gastric cancer tumorigenesis, we analyzed the functional consequences of ADCY3 overexpression." (PMID 24113161, 2013). "Significantly elevated ADCY3 expression was also observed in 80% of the Japanese gastric cancer cases analyzed." (PMID 24113161, 2013). "We found that ADCY3 is specifically upregulated in gastric cancer cell lines and tissues, and that overexpression of ADCY3 promotes tumorigenesis by increasing cell migration, proliferation, and invasiveness, through its effects on the CREB pathway." (PMID 24113161, 2013). "ADCY3 was one of the genes that were significantly overexpressed in gastric cancer samples, relative to the normal tissue." (PMID 24113161, 2013). "Knockdown of ADCY3 expression by stable shRNA in human gastric cancer cells suppressed tumor growth in a tumor xenograft model." (PMID 24113161, 2013). "ADCY3 mRNA levels in six human gastric cancer cell lines (SNU-216, SNU-638, SNU-719, AGS, KATO III, and MKN28) were significantly higher than those in normal cell lines (HDF, HMEC, and Hs738)." (PMID 24113161, 2013). "Further study on the mechanism of ADCY3 in tumorigenesis will provide the basis as a new molecular target of gastric cancer." (PMID 24113161, 2013). "We validated gastric cancer-specific upregulation of ADCY3 by using two different methods, qRT-PCR and Immunohistochemical analysis, in 229 gastric cancer samples from patients in three different groups." (PMID 24113161, 2013). "To examine the function of ADCY3 in gastric cancer development, we investigated the effects of ADCY3 overexpression or downregulation on tumorigenesis-related cellular characteristics such as cell migration, invasiveness, cell viability, and clonogenicity." (PMID 24113161, 2013). "Comparison of gene expression profiles from microarray data revealed that ADCY3 was significantly upregulated in gastric cancer tissues (P = 4.215 × 10−10)." (PMID 24113161, 2013). "Our gene expression profiling study compared cancerous and adjacent normal tissue samples from 27 Korean gastric cancer patients, and identified ADCY3 as a candidate gastric cancer gene." (PMID 24113161, 2013). "Gastric cancer-specific overexpression of ADCY3 was confirmed in 14 of 21 (66.7%) Korean gastric cancer tissues showing significantly higher ADCY3 mRNA levels than those in adjacent normal tissues." (PMID 24113161, 2013). "In addition, ADCY3 decreased apoptosis in gastric cancer cells by functioning as competing endogenous RNAs." (PMID 38545620, 2024).
gastric cancer (continued). "In gastric cancer cell lines and tissues, ADCY3 overexpression promotes tumorigenesis by upregulating the expression of matrix metalloproteinase-2 (MMP2) and metalloproteinase-9 (MMP9) via the cAMP/PKA/CREB pathway, which increases cell migration, invasion, proliferation, and colony formation." (PMID 35832555, 2022). "In summary, although further functional and clinical validation will be necessary, our results indicate that ADCY3 expression could be used as a prognostic marker for gastric cancer." (PMID 24113161, 2013). "However, our transcriptome analysis of gastric cancer tissue samples (NCBI GEO GSE30727) revealed that ADCY3 expression was specifically altered in cancer samples." (PMID 24113161, 2013). "Although ADCY3 has not yet been described in melanoma, it has been described as an oncogene in gastric cancer, in which promoter DNA hypomethylation drives its overexpression and CREB activation." (PMID 35075772, 2022). "To investigate the role of ADCY3 in tumorigenesis, we used the tumor xenograft model by implanting established gastric cancer cells (MKN28) with or without ADCY3 knockdown." (PMID 24113161, 2013).
glioma (3 papers, 2019 to 2023). A benign or malignant brain and spinal cord tumor that arises from glial cells (astrocytes, oligodendrocytes, ependymal cells). "As shown in the LRS formula, the expression of GNAI3, ACACB, ADCY3, and ACADSB emerged as the most important LMRGs that contribute to the risk signature of gliomas patients." (PMID 36860853, 2023).
adenoma (2 papers, 2021 to 2022). A neoplasm arising from the epithelium. "These new driver mutations in OR1B1 (GPCR signaling), LAMA1 (PI3K-Akt signal in CRC evolution), and ADCY3 (FGFR signaling) of adenoma evolution and cancer evolution, confirming that both colorectal adenomas and CRC were of monoclonal origin." (PMID 35785171, 2022). "New mutations were found in OR1B1 (GPCR signaling pathway) in adenoma evolution, and LAMA1 (PI3K-Akt signaling pathway) and ADCY3 (FGFR signaling pathway) in CRC evolution." (PMID 35785171, 2022). "New driver mutations were identified that developed during the evolution of both adenoma and cancer: on one hand OR1B1 (GPCR signaling pathway) was related to adenoma evolution; on the other hand, LAMA1 (PI3K-Akt signaling pathway) and ADCY3 (FGFR signaling pathway) had a role in CRC evolution." (PMID 34833475, 2021).
autism (2 papers, 2019 to 2022). Persistent deficits in social interaction and communication and interaction as well as a markedly restricted repertoire of activity and interest as well as repetitive patterns of behavior. "Since ADCY3 is associated with MDD and ASD, we asked if AC3 affects phosphorylation of other autism-associated proteins." (PMID 30814930, 2019).
autism spectrum disorder (2 papers, 2019 to 2022). A spectrum of developmental disorders that includes autism, and Asperger syndrome. "Brain transcriptome analysis of human postmortem samples has also found altered level of Adcy3 transcript in autism spectrum disorder." (PMID 36188604, 2022).
epilepsy (2 papers, 2024). A brain disorder characterized by episodes of abnormally increased neuronal discharge resulting in transient episodes of sensory or motor neurological dysfunction, or psychic dysfunction. "ADCY3 is a pivotal gene in classical ketogenic diets, which are fundamentally high in fat content, moderate in protein content, and low carbohydrates, for the treatment of epilepsy." (PMID 39195547, 2024).
melanoma (2 papers, 2020 to 2022). A malignant, usually aggressive tumor composed of atypical, neoplastic melanocytes. "In order to better understand the epigenetic regulation of Lrrk2, Inpp4b, and Adcy3 in our murine melanoma model, we analyzed the ERBBS and expression data for CpG resolution methylation levels." (PMID 35075772, 2022). "We evaluated metastatic formation in mouse lungs, a common site for melanoma metastases, by intravenously injecting 4C11+ cells silenced for Adcy3, Inpp4b, or control cells." (PMID 35075772, 2022). "Adenylate cyclase type 3 (Adcy3) and inositol polyphosphate 4‐phosphatase type II (Inpp4b) were identified as genes regulated by DNA methylation that, respectively, affect melanoma growth and metastasis." (PMID 35075772, 2022). "We analyzed LRRK2, ADCY3, and INPP4B DNA methylation and expression profiles in human melanoma cohorts to determine whether the murine model data are applicable to human melanoma biology." (PMID 35075772, 2022). "Thus, we believe that our results will require confirmation in a further larger epidemiological study in our population and others, and quantitative and functional analyses of ADCY3, CREB1 and MITF SNVs in melanoma cells." (PMID 32699307, 2020).
atherosclerosis (1 paper, 2024). A disease characterized by the build-up of fatty material and calcium deposition in the arterial wall resulting in partial or complete occlusion of the arterial lumen. "have revealed that olfactory receptor 2 (Olfr2) interacts with TLR4 in vascular macrophages leading to NLRP3 inflammasomes activation via adenylate cyclase 3 (Adcy3) to drive atherosclerosis development, provides a new target for the prevention and treatment of atherosclerosis." (PMID 38803504, 2024).
basal cell carcinoma (1 paper, 2021). A carcinoma involving the basal cells.
dyslipidaemia (1 paper, 2023). "Mutations in ADCY3 in mice cause impaired insulin sensitivity and dyslipidaemia and mice with ADCY3 knockout show increased fat mass, hyperphagia, depression-like phenotypes, and leptin resistance." (PMID 37368776, 2023).
in situ breast cancer (1 paper, 2025). "Cathepsin Z can mediate the effects of PRX, CRY2, ADCY3, and PELATON on in situ breast cancer." (PMID 39944834, 2025).
lymph node metastasis (1 paper, 2025). "ADSL, ADCY3, and NME6 were associated with lymph node metastasis, distant metastasis, and differentiation, whereas APRT and NME3 were independent of these clinical variables." (PMID 40017120, 2025).
medulloblastoma (1 paper, 2015). A malignant, invasive embryonal neoplasm arising from the cerebellum. "Medulloblastoma and the localization of ADCY3 to the base of the primary cilia, provides a compelling illustration." (PMID 26283963, 2015). "A number of experimental findings suggest that the positioning of ADCY3 in primary cilia anatomy may support a cooperative role for cAMP regulation in SHH pathway dependent medulloblastoma-genesis." (PMID 26283963, 2015).
meningioma (1 paper, 2013). A generally slow growing tumor attached to the dura mater. "Most of these genes were lowly expressed in both benign and malignant meningiomas; however, five genes (ADCY3, GAS7, LAG3, LRR32 and SPON2) showed a trend of elevated expression (>3 fold in mean values) in malignant meningiomas." (PMID 23349797, 2013).
metastatic melanoma (1 paper, 2022). A melanoma that has spread from its primary site to another anatomic site. "In our murine model, Adcy3 may play a role in tumor formation in metastatic melanoma; however, metastatic potential remained unchanged after Adcy3 knockdown." (PMID 35075772, 2022).
pneumonia (1 paper, 2024). An acute, acute and chronic, or chronic inflammation focally or diffusely affecting the lung parenchyma, caused by an infection in one or both of the lungs (by bacteria, viruses, fungi, or mycoplasma.). "Moreover, a most recent study also showed that common introgression signals of alleles ADCY3, TRPV1, and PADI2 genes from wild relatives enhanced climatic adaptation and resistance to pneumonia in domestic sheep." (PMID 39725653, 2024).
Sepsis (1 paper, 2022). Sepsis is defined as life-threatening organ dysfunction caused by a dysregulated host response to infection. "Meanwhile, the present study identified eight metabolism-related genes (NME1, NME6, POLD4, POLE4, POLR2J, POLR2L, ADCY3, and ENTPD1) in patients with sepsis and the identified metabolism-related genes may represent diagnostic and therapeutic biomarkers of sepsis." (PMID 35265105, 2022). "However, the exact role of ADCY3 in the metabolic changes in sepsis has not been identified." (PMID 35265105, 2022).
cancer (11 papers, 2008 to 2023). A tumor composed of atypical neoplastic, often pleomorphic cells that invade other tissues. "For instance, owing to the positive correlation in PTA, the cancer-associated increase of the chemokine CCL28 abundance increased the abundance of the linked adenylate cyclase ADCY3 that regulates numerous pathways, including calcium signaling." (PMID 33302383, 2020). "The comparison of mRNA levels of ADCY6 and ADCY7 in normoxic versus hypoxic samples revealed their increased hypoxic transcription in all four cancer cell types, whereas ADCY3 was unchanged or reduced." (PMID 28860539, 2017). "In our study, ADCY3 overexpression caused a considerable increase in the mobility, invasiveness, proliferation, and clonogenicity of cancer cells, whereas silencing of ADCY3 suppressed these activities." (PMID 24113161, 2013). "These genes include well annotated tumor-suppressor genes and oncogenes (e.g., TGFBR2 and MYC as well as genes that have never been previously linked to cancer in general, or to increased BC risk (including ADCY3, ATXN7, CFL1 and LPAR2)." (PMID 36991492, 2023). "ADCY3 expression may be affected by promoter CpG methylation, a well-known epigenetic mechanism for cancer-specific changes in gene expression." (PMID 24113161, 2013). "This study is the first to report that ADCY3 is involved in cancer development." (PMID 24113161, 2013). "Therefore, upregulated ADCY3 may lead to increased cell migration, invasion, and proliferation, which are characteristic of cancer." (PMID 24113161, 2013).